CRIM1 (cysteine rich transmembrane BMP regulator 1)
Description:
May play a role in CNS development by interacting with growth factors implicated in motor neuron differentiation and survival. May play a role in capillary formation and maintenance during angiogenesis. Modulates BMP activity by affecting its processing and delivery to the cell surface.
Synonyms: CRIM-1; S52
Tractability: Antibody: UniProt places it where antibodies can reach, with high confidence; UniProt predicts a signal peptide or a membrane-spanning region; its Gene Ontology location is reachable by antibodies, with medium confidence. PROTAC: ubiquitination databases record sites on it.
Gene: Protein-coding gene on chromosome 2 (36,355,731 to 36,551,135, forward strand). Ensembl gene ENSG00000150938.
Subcellular location: Secreted (Processed cysteine-rich motor neuron 1 protein); Cell membrane
Gene Ontology:
Molecular function: PDZ domain binding; insulin-like growth factor receptor activity; enzyme inhibitor activity; serine-type endopeptidase inhibitor activity
Biological process: negative regulation of BMP signaling pathway; negative regulation of osteoblast differentiation; nervous system development; insulin-like growth factor receptor signaling pathway
Cellular component: membrane; non-collagenous component of interstitial matrix; extracellular region; plasma membrane
Genetic constraint (gnomAD): Loss-of-function variants: 31 observed, 111.41 expected, observed/expected ratio (o/e) 0.28, 90% interval 0.21 to 0.38. The upper end of that interval is the gene's LOEUF score, 0.38, which puts it in group 1 of 6, group 1 being the genes least tolerant of losing a copy. Missense variants: 1,252 observed, 1,311.8 expected, observed/expected ratio (o/e) 0.95, 90% interval 0.91 to 1. Synonymous variants: 559 observed, 493.69 expected, observed/expected ratio (o/e) 1.13, 90% interval 1.06 to 1.21.
Homologues: Orthologues: chimpanzee CRIM1 (99% identical), macaque CRIM1 (99% identical), dog CRIM1 (92% identical), pig CRIM1 (91% identical), rat Crim1 (89% identical), mouse Crim1 (89% identical), rabbit CRIM1 (83% identical), guinea pig CRIM1 (82% identical), tropical clawed frog crim1 (78% identical), zebrafish crim1 (70% identical). Paralogues in human: MUC5AC (23% identical), MUC5B (22% identical), FCGBP (22% identical), OTOG (21% identical), VWF (21% identical), OTOGL (20% identical), MUC6 (18% identical), KCP (18% identical), ZAN (18% identical), MUC19 (17% identical), TECTA (17% identical), MUC2 (17% identical), and 7 more.
Diseases named in the same sentence as CRIM1 in open-access papers:
CRIM1 is named in the same sentence as 58 diseases in open-access papers, as found by Europe PMC text mining. Sharing a sentence is not in itself a finding about the gene and the disease. The quoted sentences say what the papers report.
lung carcinoma (5 papers, 2020 to 2025). "CRIM1 regulates the homeostasis of endothelial cells in the coronary vasculature, and in A549 lung cancer cells, TGFβ1-induced CRIM1 over-expression enhanced A549 cell migration and adhesion." (PMID 37887014, 2023). "For instance, SDCBP2-AS1 was upregulated in lung cancer cells and depletion of its expression could promote lung cancer cell ferroptosis by regulating miR-656-3p/CRIM1 axis." (PMID 40640983, 2025).
cataract (4 papers, 2016 to 2025). Partial or complete opacity of the crystalline lens of one or both eyes that decreases visual acuity and eventually results in blindness. "Crim1 has been implicated in cataracts in mice and is of great importance in the development of the eye in both humans and mice." (PMID 36586009, 2023). "In hypomorphic and null mutant mouse models, Crim1 has been shown to cause congenital cataracts, aphakia, and additional organ defects in the ears, urogenital tract, and kidneys." (PMID 30979021, 2019). "In addition, previous studies have shown that Crim1 mutations are responsible for congenital cataracts in subtype and null mutant mouse models." (PMID 36586009, 2023). "Therefore, we aimed to clarify how Crim1 mutations affect lens development and the molecular mechanism of cataracts in mice through comprehensive bioinformatics analysis." (PMID 36586009, 2023). "A gene that has been implicated in cataracts in mice is Crim1." (PMID 30979021, 2019). "Therefore, this study will have a certain guiding influence on the early diagnosis and intervention of congenital cataracts by clarifying how Crim1 mutations affect lens development and the molecular mechanism of cataracts in mice through comprehensive bioinformatics analysis." (PMID 36586009, 2023). "However, although congenital cataracts have been observed in Crim1 conditional and null mutant mouse models, they have not yet been observed in patients." (PMID 40114969, 2025). "Yet another explanation for the discrepancy in phenotypes is simply that heterozygosity for human CRIM1 does not cause sufficient loss-of-function to produce a cataract phenotype." (PMID 26681494, 2016).
gastric cancer (4 papers, 2021 to 2023). A primary or metastatic malignant neoplasm involving the stomach. "In gastric cancer cells, miR-665 is able to directly target and inhibit Cysteine Rich Transmembrane BMP Regulator 1(CRIM1) and MAPK1(ERK2) to decrease the proliferation of cancer cells." (PMID 37894282, 2023). "Interestingly, up-regulating the expression of CRIM1 would eliminate the inhibitory effect of miRNA-665 on gastric cancer." (PMID 34299149, 2021). "Additionally, miR-665 suppresses epithelial–mesenchymal transition (EMT) and gastric cancer progression by targeting cysteine-rich motor neuron protein 1 (CRIM1)." (PMID 34497766, 2021). "In vitro, miRNA endogenous mimics could repress gastric cancer cell lines growth by targeting the 3′-UTR of the CRIM1 gene which was found to promote the EMT process in GC cell lines." (PMID 34299149, 2021).
Microcornea (4 papers, 2016 to 2025). A congenital abnormality of the cornea in which the cornea and the anterior segment of the eye are smaller than normal. "A deletion of approximately 9 kb removing exons 15–17 and the 3′ untranslated region (UTR) of CRIM1 was reported in a family with iris and chorioretinal colobomas and microcornea." (PMID 40114969, 2025). "Heterozygous deletions predicting haploinsufficiency for the Cysteine Rich Motor Neuron 1 (CRIM1) gene have been identified in two families with macrophthalmia, colobomatous, with microcornea (MACOM), an autosomal dominant trait." (PMID 40114969, 2025). "Evidence that CRIM1 haploinsufficiency leads to defects in eye development in humans and mice suggests CRIM1 as a potential causative gene of Macrophthalmia, colobomatous, with microcornea (MACOM) and underscores the importance of CRIM1 in eye development." (PMID 38818040, 2024). "Recently, CRIM1 haploinsufficiency was implicated in the human ocular syndrome MACOM (OMIM #602499), which is characterized by iris coloboma, microcornea, and increased axial length associated with myopia." (PMID 26681494, 2016). "Recently, CRIM1 haploinsufficiency has been linked to human MACOM syndrome, an ocular disease characterized by microcornea, iris coloboma and increased axial length with severe myopia." (PMID 26681494, 2016). "In these families, a deletion of approximately 22 kilobases (kb) that included exons 14 through 17 of CRIM1 was described in a family with microcornea, coloboma of the iris, choroid, retina, and optic disc, increased axial length, myopia, mild cornea plana, and a shallow anterior chamber." (PMID 40114969, 2025). "Heterozygous deletions predicted to result in haploinsufficiency for CRIM1 have been identified in families with eye defects comprising colobomatous macrophthalmia with an increased axial length of the globe, microcornea, and coloboma of the iris, chorioretinal structures, and optic disc." (PMID 40114969, 2025). "Microcornea, coloboma, and variable expressivity, as seen in family 1, are characteristic findings for MACOM syndrome and consistent with the clinical features reported for individuals harboring the previously published CRIM1 deletion." (PMID 33418956, 2021).
breast carcinoma (3 papers, 2015 to 2023). "Gene set enrichment analysis (GSEA) was utilized to determine the cascades that are linked to CRIM1 in breast cancer." (PMID 35600360, 2022). "Oncomine analysis of CRIM1 expression in breast cancer revealed decreased CRIM1 levels in many kinds of breast carcinoma, such as infiltrative ductal breast carcinoma, infiltrative lobular breast carcinoma, and medullary breast carcinoma." (PMID 35600360, 2022). "Receiver operating characteristic (ROC) curve analysis of the relationship of CRIM1 with survival time of breast cancer patients revealed an AUC of 0.891, indicating good performance for CRIM1 in predicting survival." (PMID 35600360, 2022). "CRIM1 expression in different subtypes of breast cancer and normal tissues using the Oncomine database." (PMID 35600360, 2022). "Oncomine assessment exhibited that CRIM1 was remarkably downregulated in breast cancer compared with normal tissue, including in infiltrative ductal carcinoma, infiltrative lobular carcinoma, and medullary carcinoma." (PMID 35600360, 2022). "Breast cancer patients were then grouped into the high- and low-CRIM1 expression groups and their correlation with age, menopause, TNM stage, histological type, pathologic stage, HER2 status, and radiotherapy were investigated." (PMID 35600360, 2022). "Further researches are needed to better characterize the prognostic value of CRIM1 in breast cancer." (PMID 35600360, 2022). "Further, we adopted TIMER to examine the relationship of CRIM1 with invading immune cells in breast cancer, consisting of CD4+ T-cells, neutrophils, CD8+ T-cells, macrophage M1, B-cells, NK, endothelial cells, and Tregs." (PMID 35600360, 2022). "Investigation of the impact of CRIM1 on breast cancer prognosis using Kaplan-Meier and PrognoScan analyses revealed that reduced CRIM1 levels correlated with poorer RFS, OS, DSS, DFS, and DMFS." (PMID 35600360, 2022). "And then, the prognostic significance of CRIM1 and its co-expressed genes in breast cancer were assessed." (PMID 35600360, 2022). "Next, we divided breast cancer patients into various groups according to various clinical characteristics and compared differences in CRIM1 mRNA levels using bc-GenExMiner." (PMID 35600360, 2022). "This analysis revealed that relative to normal tissues, CRIM1 levels were remarkably lower in breast cancer tissues (χ2=10.444, p=0.001)." (PMID 35600360, 2022). "We further found that the expression of CRIM1 had a correlation with the pathological tumor stage of breast cancer, and it was obvious to observe that its expression was highest in stage I." (PMID 35600360, 2022). "Human Protein Atlas results showed that CRIM1 expression was lower than normal in breast cancer and IHC analyses revealed the expression of CRIM1 was lowest in triple-negative breast cancer." (PMID 35600360, 2022). "Here, we find that CRIM1 expression was downregulated in various subtypes of breast cancer, and it was lowest in triple-negative breast cancers." (PMID 35600360, 2022). "CRIM1 expression in different subtypes of breast cancer and normal tissues using Immunohistochemistry [n(%)]." (PMID 35600360, 2022). "Next, we evaluated CRIM1 expression in clinical specimens in relation to breast cancer clinicopathological parameters." (PMID 35600360, 2022). "BC-GenExMiner was employed to evaluate the relationship of CRIM1 expression with the clinicopathological characteristics of breast cancer." (PMID 35600360, 2022). "CRIM1 expression and survival data of breast cancer patients through the PrognoScan database." (PMID 35600360, 2022). "Relationship between CRIM1 expression and clinicopathologic parameters of breast cancer patients." (PMID 35600360, 2022). "Although CRIM1 was reported to involve in multiple cancers, its role in breast cancer is unclear." (PMID 35600360, 2022). "In addition, we performed immunohistochemistry on breast cancer and normal tissues using anti-CRIM1 antibody(ab272542) and analyzed the results." (PMID 35600360, 2022).
breast carcinoma (continued). "More researches are needed to better understand the prognostic value of CRIM1 in breast cancer." (PMID 35600360, 2022). "Our findings demonstrated that low CRIM1 expression predict poor prognosis of breast cancer and CRIM1 might be used as a possible treatment target or prognostic marker in breast cancer." (PMID 35600360, 2022). "Overall, whether the protein expression or mRNA expression of CRIM1 were lower in breast cancer than in normal breast tissues." (PMID 35600360, 2022). "Besides, we examined the expression of CRIM1 in breast cancer tissues by immunohistochemistry." (PMID 35600360, 2022). "However, the significance of CRIM1 expression in breast cancer is unclear." (PMID 35600360, 2022). "To evaluate the possible mechanisms accounting for the effects of CRIM1 on breast cancer, we performed GSEA analysis on samples with low CRIM1 levels relative to those with high CRIM1 levels." (PMID 35600360, 2022). "But in our immunohistochemical results in breast cancer specimens collected from our laboratory, HER-2 expression was positively correlated with CRIM1 expression." (PMID 35600360, 2022). "Analysis of CRIM1 protein levels in breast cancer on human protein atlas exhibited that CRIM1 protein was not expressed in cancer cells, although it was modestly and moderately expressed in myoepithelial cells and glandular cells, respectively." (PMID 35600360, 2022). "In conclusion, our findings indicated that CRIM1 was downregulated in breast cancer in contrast with non-malignant tissues and that reduced CRIM1 expression was correlated with poor prognosis." (PMID 35600360, 2022). "Consistent with sequencing and PCR results, northern blots reveal abundant short transcripts derived from both CRIM1:1 and ZEB2:2g regions, processed in MCF10A, a normal human mammary epithelial cell line, but are downregulated in both MCF7 and MDA-MB-231, two aggressive breast cancer cell lines." (PMID 25798919, 2015).
MACOM syndrome (3 papers, 2016 to 2025). "Haploinsufficiency for CRIM1 has previously been associated with MACOM syndrome, but pathogenic deletions involving this gene remain rare." (PMID 40114969, 2025). "In mice, the loss of Crim1 results in ocular malformations similar to the anomalies seen in patients with MACOM syndrome, indicating that MACOM syndrome is caused by haploinsufficiency of CRIM1." (PMID 33418956, 2021). "An approximately 22-kb deletion, spanning exons 14 through 17 of CRIM1, has been previously reported in a large family with colobomatous macrophthalmia with microcornea (MACOM) syndrome." (PMID 33418956, 2021).
microphthalmia (3 papers, 2016 to 2025). Congenital or developmental anomaly in which the eyeballs are abnormally small. "We identified a novel ENU-induced hypomorphic allele of Crim1, Crim1glcr11, which in the homozygous state causes cataract and microphthalmia." (PMID 26681494, 2016).
nasopharyngeal carcinoma (3 papers, 2020 to 2022). A carcinoma arising from the nasopharyngeal epithelium. "CircRNA CRIM1 was reported to promote nasopharyngeal carcinoma DTX chemoresistance through upregulating FOXQ1." (PMID 35659274, 2022).
ovarian carcinoma (3 papers, 2020 to 2022). A malignant neoplasm originating from the surface ovarian epithelium. "circCRIM1 was implicated in promoting ovarian cancer progression by acting as a competitive endogenous RNA (ceRNA) for the host gene CRIM1 and targeting the miR-383-5p/ZEB2 axis." (PMID 36287121, 2022). "We detected the CRIM1 mRNA in the same samples of ovarian cancer and normal ovarian tissues as above." (PMID 34847936, 2021). "We detected the expression of circCRIM1 and its parental gene cysteine rich transmembrane BMP regulator 1 (CRIM1) in ovarian cancer and normal ovarian samples via qRT-PCR." (PMID 34847936, 2021). "MTT viability assay, apoptosis assay, wound healing assay and invasion assay were used to investigate the function of circCRIM1 and CRIM1 in ovarian cancer cell lines OVCAR3 and CAOV3." (PMID 34847936, 2021). "We analyzed the expression levels of circCRIM1 and CRIM1 in ovarian cancer samples and found there was a positive correlated relationship between circCRIM1 and CRIM1 mRNA." (PMID 34847936, 2021). "CircCRIM1 and CRIM1 had higher expression in ovarian cancer than in normal ovarian tissues, and both of them promoted ovarian cancer progression in vitro." (PMID 34847936, 2021). "After CRIM1 was interfered, the viability, migration, invasion ability of ovarian cancer cell lines decreased and apoptic rate increased (P < 0.05)." (PMID 34847936, 2021). "CircCRIM1 bond with miR-145-5p to work as ceRNA of CRIM1, and both of them offered a novel insight into researches of ovarian cancer." (PMID 34847936, 2021). "CircCRIM1 and CRIM1 had a positive correlation relationship in the same cohort of ovarian cancer tissues." (PMID 34847936, 2021). "We analyzed the expression of CRIM1 mRNA and circCRIM1 in the same cohort of ovarian cancer tissues, and found that there was a positive correlation relationship between circCRIM1 and CRIM1 (P < 0.05)." (PMID 34847936, 2021). "Then we identified that CRIM1 interference inhibited cell viability, migration, invasion and promoted apoptosis in ovarian cancer cell lines." (PMID 34847936, 2021). "The results revealed that CRIM1 mRNA was higher in ovarian cancer tissues compared to normal ovarian tissues." (PMID 34847936, 2021). "Apart from this, the over-expression and knockdown of circCRIM1 in ovarian cancer cell lines positively influenced CRIM1 expression." (PMID 34847936, 2021). "Furthemore, we detected CRIM1 expression in the same cohort of ovarian cancer tissues and normal ovarian tissues, the expression of CRIM1 mRNA was higher in ovarian cancer tissues than that in normal ovarian tissues (p < 0.05)." (PMID 34847936, 2021). "CircCRIM1 and CRIM1 promoted the ovarian cancer progression and supplied a novel insight into the researches of ovarian cancer." (PMID 34847936, 2021). "Through design of siRNA, CRIM1 was knocked down in ovarian cancer cell lines CAOV3 and OVCAR3." (PMID 34847936, 2021). "Thus, CRIM1 and circCRIM1 both played cancer-promoting roles in ovarian cancer." (PMID 34847936, 2021). "Moreover, CRIM1, the parental gene of circCRIM1, promoted the progression of ovarian cancer." (PMID 34847936, 2021). "CircCRIM1 bond with miR-145-5p to work as competing endogenous RNA (ceRNA) of CRIM1, and circCRIM1 bond with miR-383-5p to improve the expression of ZEB2 in ovarian cancer." (PMID 34847936, 2021). "In a word, circCRIM1 worked as ceRNA of CRIM1 through miR-145-5p, and bond with miR-383-5p to improve ZEB2 to play the cancer-promoting roles in ovarian cancer." (PMID 34847936, 2021). "Accordingly, increased resistance to carboplatin has been reported after upregulation of miR‐193b by directly targeting CRIM1 and IFIT2 in ovarian cancer cells." (PMID 33072537, 2020). "A few articles have revealed the cancer-promoting effects of CRIM1, but there was no comparative study on the effects of CRIM1 in ovarian cancer." (PMID 34847936, 2021). "However, there was no comparative report about the function of CRIM1 and circCRIM1 in ovarian cancer." (PMID 34847936, 2021).